GAD1 (glutamate decarboxylase 1)
Diseases named in the same sentence as GAD1 in open-access papers (continued):
Sharing a sentence is not in itself a finding about the gene and the disease.
panic disorder (10 papers, 2012 to 2023). An anxiety disorder characterized by multiple unexpected panic attacks with persistent concern of recurring attacks. "Specific SNPs and haplotypes (SNPs, rs769407, rs3791851, rs769395) showed phobias and GAD1 rs3749034 showed association with panic disorder in female population." (PMID 31435520, 2018). "Several single nucleotide polymorphisms in GAD1 gene are associated with variety of anxiety disorders, including generalized anxiety disorder, panic disorder, agoraphobia and depression." (PMID 31435520, 2018). "Another important gene, glutamate-decarboxylase 1 (GAD1), encoding a crucial glutamatergic metabolic factor, is undermethylated in patients with panic disorder." (PMID 30323739, 2018). "Further genetic studies on psychiatric disorders are in line with our tentative finding of gender-specific enrichment of GAD1 risk alleles in panic disorder." (PMID 22662185, 2012). "In conjunction with the present genetic data, convergent lines of evidence suggest that GAD1 and its gene product are implicated in the pathophysiology of panic disorder." (PMID 22662185, 2012). "In this paper, we present the first systematic evaluation of gender-dependent associations of common SNP variation in GAD1 with panic disorder." (PMID 22662185, 2012). "Gender-wise association of GAD1 polymorphisms displaying gender-specific risk allele enrichment with panic disorder." (PMID 22662185, 2012). "A recent twin study estimated the heritability of panic disorder at 48% and an independently conducted genome-wide linkage scan yielded susceptibility loci at chromosomal regions 2q (including GAD1) and 15q." (PMID 22662185, 2012). "The question of whether and how GAD1 gene methylation affects PD has tremendous importance for improving our understanding of the pathogenic mechanism of panic disorder." (PMID 35686186, 2022). "Although largely insignificant, these results lend qualitative support to our hypothesis that GAD1 alleles may have a different impact on panic disorder susceptibility in both genders." (PMID 22662185, 2012). "Genotype×gender interaction analysis of common GAD1 alleles associated with panic disorder." (PMID 22662185, 2012). "Panic disorder patients had significantly lower methylation in the GAD1 promoter region on Cytosine-phosphate-guanine (CPG) 7 than HCs (t = 2.380, p = 0.021)." (PMID 35686186, 2022). "And furthermore, to explore the correlation between GAD1 methylation, brain gray matter volume and Panic Disorder Severity Scale (PDSS) scores." (PMID 35686186, 2022). "Recent study of epigenetic processes, the study included 65 patients with panic disorder and matched healthy controls, and assessed DNA methylation status at 38 GAD1 promoter/intron 2 and 10 GAD2 promotor CpG sites." (PMID 31435520, 2018). "In summary, our study provides supporting evidence for gender differences in the role of GAD1 variation for the pathogenesis of panic disorder, but is far from conclusive." (PMID 22662185, 2012). "Studies in larger samples and subsequent meta-analysis are thus needed to unequivocally prove a possible female-specific contribution of the GAD1 gene in panic disorder." (PMID 22662185, 2012). "The present study investigated whether GAD1 gene methylation impacted panic disorder severity and whether GMV played a mediating role in this relationship." (PMID 35686186, 2022). "We hypothesized that GMV of PoCG and ANG mediates the relationship between GAD1 methylation and panic disorder severity." (PMID 35686186, 2022). "Thus, the current study sought to explore the differences in whole brain gray matter volume and GAD1 gene promoter methylation levels between patients with panic disorder and the normal population." (PMID 35686186, 2022). "Glutamate decarbodylases 1 (GAD1) hypomethylation was also specific on panic disorder patients." (PMID 31435520, 2018).
panic disorder (continued). "This study aimed to test the hypothesis that the relationship between glutamic acid decarboxylase (GAD) 1 gene methylation and severity of clinical symptoms of panic disorder (PD) is mediated by the effect of GAD1 gene methylation on gray matter volume (GMV) and the effect of GMV on PD." (PMID 35686186, 2022). "In panic disorder, hypomethylation of monoamine oxidase A (MAOA) and glutamate decarboxylases 1 (GAD1) genes have been evident in recent studies." (PMID 32499729, 2020). "Our findings suggest that cg12 site methylation of GAD1 may affect the development of PoCG and ANG GMV and further participate in the pathophysiology of panic disorder." (PMID 35686186, 2022). "Another study suggested that patients with panic disorder exhibited significantly lower average GAD1 methylation than HCs, though no methylation alterations were observed for the GAD2 gene." (PMID 35686186, 2022). "Although evidence suggests that epigenetic alterations of GAD1 gene and gray matter volumes alterations of PoCG and ANG play an important role in the onset and maintenance of panic disorder, whether GAD1 methylation influences GMV of PoCG and ANG in PD has not yet been confirmed." (PMID 35686186, 2022).
Hypoglycemia (8 papers, 2013 to 2024). A decreased concentration of glucose in the blood. "GAD1 mRNA levels in this cell population were unaffected by hypoglycemia, whereas GAD2 gene expression was inhibited." (PMID 38902332, 2024). "Single-cell multiplex qPCR analyses of laser-catapult-microdissected VMNdm versus VMNvl GAD65/67-ir neurons show that these cell subpopulations exhibit dissimilar GLUT2-dependent GAD1 and -2 transcriptional responses to hypoglycemia." (PMID 38902332, 2024). "Notably, baseline ratios of GAD2 versus GAD1 transcript profiles varied between the two divisions, and were affected by hypoglycemia in each site, as this ratio increased in VMNdm neurons, but declined in VMNvl cell samples." (PMID 38902332, 2024).
cleft palate (7 papers, 2009 to 2023). Cleft palate is a fissure type embryopathy that affects the soft and hard palate to varying degrees. "In mouse and rat models, Gad1 played a role in the normal development of the palate, while a study on the role of miRNAs in the regulation of CP genes found that variants in GAD1 significantly contributed to the human cleft palate phenotype." (PMID 36830605, 2023). "Further studies demonstrated that the presence of cleft palate is due to a defect of foetal oral movement of the tongue during palatal development and Gad1 is specifically required in the CNS for normal palatal formation." (PMID 32282878, 2020). "Except for DISP1, all these genes have been associated with cleft palate in mouse models, whereas only LHX8 and GAD1 have been associated with cleft palate disorders in humans." (PMID 19557186, 2009). "Interestingly only one presented with cleft palate, which has been suggested to be one of the key features in the GAD1 animal models." (PMID 32705143, 2020). "The phenotype of patients differed from Gad1 KO mice; some patients survived up to 10 years of age, and 30% of patients did not have a cleft palate." (PMID 33325157, 2021). "The lethality without cleft palate observed in a subpopulation of Gad1−/− rats also supports their hypothesis." (PMID 33293518, 2020).
prostate carcinoma (6 papers, 2013 to 2024). A carcinoma that arises from epithelial cells of the prostate gland. "Moreover, the combination of clinicopathological factors associated with GAD1 expression in prostate cancer to create a prognostic nomogram revealed that the combined index better evaluated patients' PFI (C-index = 0.782, p = 1.94e−14)." (PMID 37904122, 2023). "Given the significant correlation of GAD1 mutation and methylation with prostate cancer clinicopathology, this study also explored the interaction of GAD1 expression, copy number and methylation with the immune microenvironment in prostate cancer." (PMID 37904122, 2023). "For instance, glutamate decarboxylase 1 (GAD1) was found to promote prostate cancer progression and decrease the therapeutic effect of docetaxel or enzalutamide." (PMID 39335669, 2024). "Preliminary in vitro experiments confirmed that GAD1 promotes prostate cancer progression and metastasis, as well as down-regulates sensitivity to enzalutamide and docetaxel." (PMID 37904122, 2023). "Only one study has preliminarily demonstrated using immunohistochemistry that GAD1 is highly specific and sensitive in benign and malignant prostate tissues.Thus, GAD1 is a promising candidate for the exploration of prostate cancer." (PMID 37904122, 2023). "RT-PCR validation of the available prostate cancer cell lines in our laboratory revealed high GAD1 expression in LNCaP and PC3 than in RWPE1 cells; thus these were selected for subsequent validation." (PMID 37904122, 2023). "GAD1 promoter methylation levels were significantly higher in prostate cancer than in normal tissue and were significantly higher in older patients." (PMID 37904122, 2023). "Then, the Tumor Immune Dysfunction and Exclusion algorithm predicted good responsiveness to immune checkpoint inhibitors in drug-resistant prostate cancers with the low-GAD1 genotype (p = 3.5e−05)." (PMID 37904122, 2023). "In the current study, comprehensive bioinformatics analysis was performed to identify GAD1 in many drug-resistant prostate cancer gene sets." (PMID 37904122, 2023). "The relationship between GAD1 expression and prostate cancer clinic-pathological features was further investigated using the “survival R package”." (PMID 37904122, 2023). "Immunohistochemistry of patients with prostate cancer at our medical center showed significantly higher expression of GAD1 in prostate cancer tissue compared to that in paracancerous tissue." (PMID 37904122, 2023). "This research confirmed that GAD1 was a hub gene in the progression and development of drug resistance in prostate cancer." (PMID 37904122, 2023). "RT-PCR, immunohistochemistry, cell phenotype and drug sensitivity experiments further demonstrated that GAD1 promoted prostate cancer progression and decreased the therapeutic effect of docetaxel or enzalutamide." (PMID 37904122, 2023). "Increased GABA and GAD1 expression are involved in prostate cancer cell migration, and GAD1 is a specific marker for prostate cancer tissues because GAD1 expression is positively correlated with a higher Gleason score and poorer prognosis." (PMID 36814556, 2023). "Subsequently, the promoter methylation level of GAD1 in prostate cancer was explored through the UALCAN web resource." (PMID 37904122, 2023). "Interestingly, only GAD1 was confirmed as the hub drug-resistant gene affecting OS in prostate cancer." (PMID 37904122, 2023). "Glutamate decarboxylase 1 (GAD1) was tentatively identified by bioinformatic analysis as an hub gene for the development of drug resistance, including docetaxel and enzalutamide, in prostate cancer." (PMID 37904122, 2023).
prostate carcinoma (continued). "Furthermore, by exploring gene mutations, methylation, and the tumor immune cell microenvironment, GAD1 was shown to have an important physiological and immunological role in prostate cancer." (PMID 37904122, 2023). "Furthermore, the unique overexpression of GAD1 mRNA in a select cohort of castrate-resistant prostate cancer cell lines was revealed." (PMID 24551133, 2014). "Furthermore, for prostate cancer patients with high GAD1 expression, treatment with immune checkpoint blockade and anti-programmed cell death protein 1 antibodies might be more efficacious." (PMID 37904122, 2023). "Consequently, GAD1 may serve as a new target and prognostic biomarker for prostate cancer treatment and response to drug resistance." (PMID 37904122, 2023). "Consequently, whether GAD1 can accelerate the progression of prostate cancer and the development of drug resistance by affecting the tumor immune microenvironment is an area worth exploring, and its implications for prostate cancer treatment are significant." (PMID 37904122, 2023). "It has been documented previously that GAD1-mediated GABA synthesis and signaling through GABA-B receptors facilitate the expression of matrix metalloproteinases and invasion of prostate cancer cells." (PMID 24551133, 2014). "We have observed that GAD1 is up-regulated in three out six cancer types under study, namely colon, liver and lung adenocarcinoma, and GAD2 is up-regulated in prostate cancer." (PMID 23967163, 2013). "Third, this study did not provide insight into the specific mechanisms by which GAD1 affects prostate cancer." (PMID 37904122, 2023). "Second, this study lacked in vivo data and only verified GAD1 function in prostate cancer at the in vitro level." (PMID 37904122, 2023). "Furthermore, GAD1 was found to be expressed in castrate-resistant prostate cancer cell lines, but not androgen-responsive cell lines." (PMID 24551133, 2014). "However, the clinical significance of GAD1 in castrate-resistant prostate cancer remains to be clarified, as the number of GAD1-overexpressing prostate cancers identified in the public databases were small and could not be accurately correlated with castrate-resistant disease." (PMID 24551133, 2014).
respiratory failure (6 papers, 2020 to 2025). The significant impairment of gas exchange within the lungs resulting in hypoxia, hypercarbia, or both, to the extent that organ tissue perfusion is severely compromised. "It has been reported that neonatal death in Gad1−/− mice is caused by respiratory failure rather than impairment of suckling." (PMID 33413507, 2021).
Stroke (6 papers, 2015 to 2023). Sudden impairment of blood flow to a part of the brain due to occlusion or rupture of an artery to the brain. "Conversely, the fact that GAD1 expression is increased when PACAP is injected 1, 6, and 15 h after reperfusion suggests that PACAP also contributes to restore altered GABA levels after stroke, which must in turn reduce neuronal hyperexcitability." (PMID 33551991, 2020). "Interestingly, several genes such as GAD1, GJB6, GJD2, and AQP4 known to be induced or repressed by those early events of stroke are regulated in an opposite manner by PACAP which contributes to explain how PACAP protects the brain after stroke." (PMID 33551991, 2020).
breast carcinoma (5 papers, 2007 to 2023). "And the GAD1 overexpression also partially recovered the GPT2 depletion-reduced breast cancer migration." (PMID 36923530, 2023). "In the meantime, GAD1 overexpression facilitated breast cancer migration." (PMID 36923530, 2023).
gastric cancer (5 papers, 2019 to 2026). A primary or metastatic malignant neoplasm involving the stomach. "In contrast to previous findings that reported an elevated GAD1 expression in oral, nasopharyngeal, and gastric cancers, we detected a significant decrease in GAD1 expression in cervical cancer tissues." (PMID 31465717, 2020). "In addition, an increased expression of GAD1 has been reported in nasopharyngeal, breast, and gastric cancers." (PMID 37568704, 2023).
glioma (5 papers, 2009 to 2026). A benign or malignant brain and spinal cord tumor that arises from glial cells (astrocytes, oligodendrocytes, ependymal cells). "Our study found that GAD1 expression is downregulated in glioma, correlating with poor prognosis in glioma patients." (PMID 41844572, 2026). "Therefore, in GB, GABAergic signaling may be exploited both to fuel metabolic process using glutamine through increased GAD1 expression, and to promote oncogenic neuron–glioma interactions." (PMID 40685688, 2025). "Eight promoter-hypermethylated genes (ANKDD1A, GAD1, HIST1H3E, PCDHA8, PCDHA13, PHOX2B, SIX3, and SST) were confirmed in primary glioma and cell lines." (PMID 21962230, 2011). "The methylation levels of seven gene promoters (ANKDD1A, GAD1, SIX3, SST, PHOX2B, PCDHA8, and HIST1H3E) in glioma patients and cell lines were significantly higher than those in non-tumor controls (p < 0.01)." (PMID 21962230, 2011). "In addition, we found that the percentages of promoter methylation in the ANKDD1A and PHOX2B, but not the GAD1, HIST1H3E, PCDHA8, PCDHA13, SIX3 and SST, were associated negatively with the differentiation degrees of human gliomas." (PMID 21962230, 2011). "The GAD1, HIST1H3E, PCDHA8, PCDHA13, SIX3 and SST may regulate the progression of glioma." (PMID 21962230, 2011).
lung adenocarcinoma (5 papers, 2013 to 2023). A carcinoma that arises from the lung and is characterized by the presence of malignant glandular epithelial cells. "Currently, GAD1 had been shown to be associated with growth and immunosuppression in many tumors, including non-small cell lung cancer, lung adenocarcinoma, colorectal cancer, glioblastoma and others." (PMID 37904122, 2023). "In parallel, high GAD1 levels were also shown to correlate with the pathological stage of patients with lung adenocarcinoma, positively correlating with metastasis and with worse recurrence-free survival." (PMID 32183400, 2020). "In a previous genome‐wide screening, we identified hypermethylated CpG islands around glutamate decarboxylase 1 (GAD1) in lung adenocarcinoma (LADC)." (PMID 31207151, 2019).
omphalocele (5 papers, 2010 to 2023). Omphalocele is an embryopathy classified in the group of abdominal celosomias and is characterized by a large hernia of the abdominal wall, centered on the umbilical cord, in which the protruding viscera are protected by a sac. "Several studies demonstrated that both the cleft palate and the omphalocele seen in Gad1−/− mice are the consequence of reduced foetal movements." (PMID 32282878, 2020). "In agreement, rats with a deletion of the gene encoding GAD65 (Gad2) or the gene encoding GAD67 (Gad1), leads to GABA reduction and palate deformation, while double GAD65/GAD67 knockout mice exhibit an increased chance of cleft palate, omphalocele and abnormal spine curvature (kyphosis)." (PMID 37108127, 2023). "Furthermore, no apparent malformations, such as the cleft palate or omphalocele, were observed in Gad1−/− mice." (PMID 33293518, 2020).
psychosis (5 papers, 2007 to 2021). "While studies in the literature on GAD1 in psychosis were conducted primarily on postmortem brain samples, the current study is the first to examine GAD1 expression levels in human blood using qPCR." (PMID 28122016, 2017). "Follow up studies have confirmed changes in the expression in Gad1 mRNA, and other GABAergic molecules such as PV, Sst, and NPY, in individuals with psychosis." (PMID 25116473, 2014).
Seizure (5 papers, 2014 to 2025). A seizure is an intermittent abnormality of nervous system physiology characterized by a transient occurrence of signs and/or symptoms due to abnormal excessive or synchronous neuronal activity in the brain. "GAD1 was associated with an increase in posttraumatic seizure (PTS) risk due to excitotoxicity associated with gamma‐amino butyric acid (GABA) transmission after acute TBI." (PMID 31908160, 2020).
autism spectrum disorder (4 papers, 2022 to 2026). A spectrum of developmental disorders that includes autism, and Asperger syndrome. "Additionally, the GAD1 gene has been reported in the literature to be related to multiple neurological traits and disorders including Cognitive performance, Cognitive performance (MTAG) and attention deficit hyperactivity disorder, autism spectrum disorder and intelligence." (PMID 37680967, 2023).